Y_RNA (Y RNA )
Gene: Miscellaneous RNA gene on chromosome 5 (144,087 to 144,197, reverse strand). Ensembl gene ENSG00000199540.
Homologues: Orthologues: chimpanzee Y_RNA (100% identical), macaque Y_RNA (92% identical). Paralogues in human: Y_RNA (87% identical), RNY1P5 (86% identical), Y_RNA (86% identical), Y_RNA (85% identical), Y_RNA (84% identical), Y_RNA (83% identical), RNY1 (82% identical), Y_RNA (82% identical), Y_RNA (81% identical), RNY1P1 (80% identical), Y_RNA (80% identical), RNY1P11 (79% identical), and 92 more.